GADD45B (growth arrest and DNA damage inducible beta)
Diseases named in the same sentence as GADD45B in open-access papers (continued):
Sharing a sentence is not in itself a finding about the gene and the disease.
Arthritis (2 papers, 2019 to 2025). Inflammation of a joint. "Furthermore, GADD45β deficiency mice in collagen-induced arthritis (CIA) showed significantly lower arthritis severity and joint destruction, elevated IL-10 expression, decreased IL-17 production, and increased Treg cells compared with WT mice." (PMID 40083548, 2025). "The research showed that GADD45β attenuated K/BxN serum-induced arthritis but exacerbated CIA-induced arthritis." (PMID 40083548, 2025). "Moreover, in a KB/xN serum-induced arthritis model, GADD45β-/- mice exhibited a significant increase in JNK phosphorylation and a worsening of arthritic symptoms." (PMID 40083548, 2025). "GADD45β has been observed to have opposing effects on K/BxN serum- and CIA-induced arthritis in mice." (PMID 40083548, 2025). "While producing no obvious phenotypes in unchallenged animals, genetic Gadd45b disruption was shown to enhance local inflammation and immune responses in experimental mouse models of arthritis, multiple sclerosis and oncogenesis." (PMID 31080744, 2019).
brain cancer (2 papers, 2019 to 2023). A primary or metastatic malignant neoplasm affecting the brain. "In summary, in this study, efforts were made to determine that CuE is an effective inhibitor of brain cancer cell lines medicated by GADD45β." (PMID 30912292, 2019). "Previous studies have suggested that in brain cancer cells, cell-cycle arrest was achieved by downregulating the expression of cdc2 and cyclin B1 proteins and disrupting the cdc2/cyclin B1 complex through the upregulation of GADD45β." (PMID 37886957, 2023). "Protein analysis revealed that GADD45β was significantly reduced after GADD45β was silenced, whereas quantitative PCR analysis revealed that the higher expression levels of GADD45β mRNA in CuE‐treated brain cancer cells were significantly decreased after GADD45β was silenced." (PMID 30912292, 2019).
cervical cancer (2 papers, 2016 to 2025). A primary or metastatic malignant neoplasm involving the cervix. "YM Cheng found that sulforaphane may dissociate the cyclin B1/CDK1 complex by up-regulating GADD45B protein, thereby arresting in the G2/M phase and inhibiting the proliferation of cervical cancer." (PMID 40855561, 2025). "The role that SFN may plays in the inhibition of tumor growth was highlighted by the delay of mitosis through the down-regulation of cyclin B1 and the dissociation of the cyclin B1/CDC2 complex by GADD45β in cervical cancer cell lines." (PMID 27626412, 2016).
chronic kidney disease (2 papers, 2020 to 2021). Impairment of the renal function secondary to chronic kidney damage persisting for three or more months. "A recent report suggests that ablation of GADD45β ameliorates the inflammation and renal fibrosis caused by unilateral ureteral obstruction (UUO) in a chronic kidney disease mouse model." (PMID 34867947, 2021). "Here, we examined the effect of Gadd45β deletion on cell proliferation and apoptosis, inflammation, and renal fibrosis in an early chronic kidney disease (CKD) mouse model following unilateral ureteral obstruction (UUO)." (PMID 32570293, 2020).
chronic lung disease (2 papers, 2020). According to the definitions of the American and British Thoracic Societies, including pulmonary functional tests, X-rays, and CT scans for items such as fibrosis, bronchiectasis, bullae, emphysema, nodular or lymphomatous abnormalities. "Some of the common gene targets like GADD45B needs further attention and characterization especially in the chronic lung diseases like COPD and IPF." (PMID 32702724, 2020).
chronic myeloid leukemia (2 papers, 2019 to 2023). "KEGG analysis in the BaF3-T315 cells showed that the chronic myeloid leukemia signaling pathway (genes such as Cdk4, Tgfbr1, Gadd45b, Mdm2, Gadd45g, Polk, Rb1, Ctbp1, and Cdkn2a were enriched) was involved in the I13 treatment." (PMID 37124196, 2023). "Another study reported that a loss of GADD45B was associated with upregulation of JNK and signal transducer and activator of transcription (STAT) 5, resulting in cell proliferation and inhibition of apoptosis in tumorigenesis of chronic myeloid leukemia." (PMID 31296259, 2019).
glomerulosclerosis (2 papers, 2020 to 2025). A hardening of the kidney glomerulus caused by scarring of the blood vessels. "Further, the loss of Dicer in mice also causes progressive glomerulosclerosis and kidney failure, with a marked increase in Gadd45b expression as identified by microarray analyses of injured podocytes." (PMID 33208557, 2020). "Loss of Gadd45b results in reduced albuminuria, kidney failure, and glomerulosclerosis." (PMID 33208557, 2020).
Hepatic steatosis (2 papers, 2021 to 2024). Steatosis is a term used to denote lipid accumulation within hepatocytes. "Expression of Rbm3 and Gadd45b and their potential impacts on liver metabolism could be a consequence and/or a cause of the reduced adiposity and hepatic steatosis of the Csf1rko." (PMID 34081701, 2021). "It is generally believed that Gadd45β plays a crucial role in lipid metabolism, but changes of its expression in liver steatosis are still uncertain." (PMID 39653679, 2024). "The impact of Gadd45β on metabolism gradually changes during the progression of fatty liver, and its impact on cell damage and inflammation dominates the subsequent progression of fatty liver inflammation." (PMID 39653679, 2024). "Furthermore, as fatty liver progresses to hepatitis and liver fibrosis, the functional focus of Gadd45β changes with time." (PMID 39653679, 2024). "It is worthy mentioned that Gadd45β can help alleviate fatty liver." (PMID 39653679, 2024). "Thus, the regulatory network complicates the assessment of Gadd45β's benefits in fatty liver disease." (PMID 39653679, 2024).
insulinoma (2 papers, 2016 to 2021). "It was also reported that Gadd45β overexpression inhibited JNK activation and suppressed IL-1β-induced apoptosis in the insulinoma cells." (PMID 34769468, 2021).
kidney failure (2 papers, 2020). An acute or chronic condition that is characterized by the inability of the kidneys to adequately filter the blood. "Deletion of Gadd45b in the Gak-KO mice was also associated with reduced proteinuria and kidney failure, and increased survival correlated with reduced podocyte injury and stabilization of podocyte adhesion." (PMID 33208557, 2020).
liver diseases (2 papers, 2017 to 2024). "In conclusion, we explore the potential of targeting Gadd45β as a therapeutic strategy for liver diseases." (PMID 39653679, 2024). "This article aims to systematically review the role of Gadd45β in liver diseases, including its regulatory mechanism on expression and involvement in liver cell damage, inflammation, fibrosis and HCC." (PMID 39653679, 2024). "This article aims to elucidate the mechanism by which Gadd45β operates in liver diseases and assess its potential as a therapeutic target." (PMID 39653679, 2024). "Liver fibrosis is a crucial process in the progression of liver diseases, with Gadd45β being involved in such process." (PMID 39653679, 2024). "Meanwhile, ZY0511 has emerged as a promising therapeutic agent for HCC by upregulating Gadd45β, thereby proposing a novel combination strategy for treating liver diseases." (PMID 39653679, 2024). "HCC is a severe liver disease and Gadd45β also plays an important role in its occurrence and development." (PMID 39653679, 2024). "Although significant progress in elucidating the role of Gadd45β in liver diseases has been made, its specific mechanism of action and potential as a therapeutic target remain unclear." (PMID 39653679, 2024). "With further research, Gadd45β may become an important therapeutic target for liver diseases, bringing new hope to patients." (PMID 39653679, 2024). "Gadd45β plays a significant role in the pathogenesis of liver diseases." (PMID 39653679, 2024). "In addition to liver disease‐induced damage, the induction of Gadd45β by drug‐induced liver damage is well‐documented." (PMID 39653679, 2024). "Accordingly, Mef2c and Gadd45b, corresponding to lncRNA 2900097C17Rik, may be involved in liver diseases in a bacterial or viral response-like manner." (PMID 29383134, 2017). "Gadd45β is involved in liver cell damage, inflammation, fibrosis and HCC, playing an important role in liver diseases." (PMID 39653679, 2024). "The current research has not fully elucidated the exact function and mechanism of Gadd45β in liver fibrosis, and future research may further reveal its potential value in the treatment of liver diseases." (PMID 39653679, 2024).
liver fibrosis (2 papers, 2021 to 2024). "Recent studies have identified that Gadd45β deficiency promotes senescence and alleviates liver fibrosis, whereas Gadd45α can play a protective role in liver fibrosis." (PMID 39653679, 2024). "The therapeutic effect of 3‐deoxyadenosine A (DZNep) as an epigenetic drug in liver fibrosis is related to Gadd45β regulation by EZH2." (PMID 39653679, 2024). "This is inconsistent with the results in genetic animals, which suggests the involvement of Gadd45β in the occurrence of liver fibrosis and its incongruous role beyond regulating the cell cycle." (PMID 39653679, 2024). "Inhibition of EZH2 helps to alleviate liver fibrosis by reducing H3K27me3 recruitment and increasing the expression of cell cycle regulators, including Gadd45β." (PMID 39653679, 2024). "The in vitro and in vivo data collectively suggest that EZH2 and JMJD3 coordinately modulate HSCs activation and liver fibrosis through, at least in part, epigenetically regulating Bambi, Cdkn1a, Gadd45a and Gadd45b." (PMID 33391480, 2021). "After considering various articles exploring expression levels and mechanisms of Gadd45β, most studies currently indicate that Gadd45β can promote liver fibrosis, although its molecular regulatory mechanism remains unknown." (PMID 39653679, 2024). "Currently, the expression of Gadd45β in liver fibrosis is unclear." (PMID 39653679, 2024). "The therapeutic effects of DZNep as epigenetic drug in liver fibrosis are associated with the regulation of EZH2 towards direct target genes encoding TGF-β1 pseudoreceptor BAMBI, anti-inflammatory cytokine IL10 and cell cycle regulators CDKN1A, GADD45A and GADD45B, which are also regulated by JMJD3." (PMID 33391480, 2021). "Significant downregulation of the expression of Gadd45α, rather than of Gadd45β or Gadd45γ, was detected in mouse liver fibrosis tissue induced by CCl4 and isolated HSCs, accompanied with activation of the TGFβ–SMAD signalling pathway." (PMID 39653679, 2024).
lung adenocarcinoma (2 papers, 2023 to 2024). A carcinoma that arises from the lung and is characterized by the presence of malignant glandular epithelial cells. "The expression of both GADD45B and PPP3CC was remarkably downregulated in lung adenocarcinoma, as well as in numerous other cancer types, in line with the reported downregulation of GADD45B and PPP3CC in various cancers." (PMID 38167059, 2024). "Based on TCGA and GTEx databases, the expression levels of FOS, GADD45B, and EGR1 in liver hepatocellular carcinoma (LIHC) and lung adenocarcinoma (LUAD) were lower than those in normal samples." (PMID 37405258, 2023). "As GADD45B and PPP3CC are activated by shikonin to suppress cell proliferation and metastasis in lung adenocarcinoma, we speculated whether their expression was correlated with patient prognosis." (PMID 38167059, 2024). "Therefore, we preferentially selected GADD45B and PPP3CC as candidate targets for shikonin in lung adenocarcinoma cells." (PMID 38167059, 2024). "Taken together, all these results demonstrated that both GADD45B and PPP3CC were downregulated in lung adenocarcinoma as TSGs and could be activated by shikonin through the MAPK signaling pathway." (PMID 38167059, 2024). "Interestingly, among these selected TSGs, GADD45B and PPP3CC have been reported as tumor suppressors that inhibit cancer cell proliferation and invasion in various cancers; however, their roles in lung adenocarcinoma remain unknown." (PMID 38167059, 2024). "The expression of both GADD45B and PPP3CC was not related to gender, that is, no matter what gender is, their expressions were distinctly lower in lung adenocarcinoma than those of normal ones." (PMID 38167059, 2024).
lymph node metastasis (2 papers, 2021 to 2023). "GADD45B was related to distant metastasis but not to Gleason score, prostate-specific antigen level, T stage, or lymph node metastasis and indicated a good prognosis." (PMID 34490266, 2021). "Furthermore, the clinical samples from our hospital demonstrated that the level of GADD45B was not related to Gleason score, T stage, and lymph node metastasis (p > 0.05)." (PMID 34490266, 2021). "The results showed that a high RNA level of GADD45B was related to a low T stage (p = 0.042) but not to Gleason score, PSA level, and lymph node metastasis (p > 0.05)." (PMID 34490266, 2021). "Similarly, the GADD45B protein level was not related to age, Gleason score, PSA level, T stage, or lymph node metastasis (p > 0.05)." (PMID 34490266, 2021).
myeloid leukemia (2 papers, 2010 to 2025). A clonal proliferation of myeloid cells and their precursors in the bone marrow, peripheral blood, and spleen. "Initially, GADD45β encoded by MyD118 was identified as a myeloid differentiation primary response gene activated by IL-6 in murine myeloid leukemia cells upon induction of terminal differentiation." (PMID 20942912, 2010). "Another gene of the GADD45 family, GADD45β (designated initially as MyD118), was identified as a primary response gene transiently induced by IL-6 in myeloid leukemia cell lines." (PMID 40083548, 2025).
non-alcoholic fatty liver disease (2 papers, 2023 to 2024). "Recently, evidence has accumulated that Gadd45b deficiency promotes premature aging and skin senescence, and FGFR1 has been reported to ameliorate impaired lipid metabolism in mice with non-alcoholic fatty liver disease through upward regulation of the FGF21/FGFR1 pathway." (PMID 37958806, 2023). "In the study of the pathogenic role of dysfunctional subcutaneous white adipose tissue in the progression of nonalcoholic fatty liver disease (NAFLD), RNA sequencing analysis showed that Gadd45β expression paralleled the degree of steatosis." (PMID 39653679, 2024).
Obesity (2 papers, 2016 to 2024). Accumulation of substantial excess body fat. "Prompted by our results that GADD45β loss can affect glucose homoeostasis in obesity, we tested whether restoration of liver GADD45β can improve metabolic homoeostasis in type 2 diabetes." (PMID 27137487, 2016). "Using whole‐body knockout mice as well as liver/hepatocyte‐specific gain‐ and loss‐of‐function strategies, we revealed a role for liver GADD45β in the coordination of liver fatty acid uptake, through cytoplasmic retention of FABP1, ultimately impacting obesity‐driven hyperglycaemia." (PMID 27137487, 2016).
osteoarthritis (2 papers, 2013 to 2025). A noninflammatory degenerative joint disease occurring chiefly in older persons, characterized by degeneration of the articular cartilage, hypertrophy of bone at the margins and changes in the synovial membrane. "The results indicated that MCL1, JUN, and GADD45B exhibited relatively high AUC values, highlighting their significant classification ability and potential as biomarkers for osteoarthritis." (PMID 40826778, 2025). "LASSO regression and the Boruta algorithm validated the significant predictive ability of genes such as MCL1, JUN, and GADD45B, with their high AUC values indicating potential as osteoarthritis biomarkers." (PMID 40826778, 2025).
osteosarcoma (2 papers, 2023 to 2025). A usually aggressive malignant bone-forming mesenchymal neoplasm, predominantly affecting adolescents and young adults. "While GAS5 is downregulated in numerous cancers, including osteosarcoma, the role that GADD45b plays in cancer is less clear, as there are reports of decreased expression of GADD45b in some cancers and increased expression in other cancers." (PMID 37349371, 2023).
pituitary tumor (2 papers, 2012 to 2022). A benign or malignant neoplasm affecting the pituitary gland. "As a novel pituitary tumor suppressor, microarray data showed the loss of GADD45B in gonadotrope tumors where its repression modulates cell proliferation, survival, and tumorigenicity." (PMID 23110778, 2012). "According to microarray studies, Gadd45b was downregulated 68-fold in pituitary tumors, and its loss may contribute to tumorigenesis or progression." (PMID 36311022, 2022). "The Gadd45b protein has been studied in neurological tumors, mainly in pituitary tumors, fibrillary astrocytoma, and adult neural tube cell tumors." (PMID 36311022, 2022). "Thus, this study identified Gadd45b as a novel pituitary tumor suppressor whose re-expression blocks proliferation, survival, and tumorigenesis." (PMID 36311022, 2022).
psoriasis (2 papers, 2021 to 2025). An autoimmune condition characterized by red, well-delineated plaques with silvery scales that are usually on the extensor surfaces and scalp. "Here, we analyzed the expression of GADD45a and GADD45b in the skin, dendritic cells and circulating T cells in a cohort of psoriasis patients and their regulation by inflammatory signals." (PMID 34272424, 2021). "T cells from psoriasis patients expressed higher levels of GADD45b after stimulation with a mixture of IL-12 and IL-18 compared to controls." (PMID 34272424, 2021). "To explore the role GADD45a and GADD45b in psoriasis, we first analyzed the expression of GADD45a and GADD45b genes in lesional and non-lesional skin samples from 30 patients (17 male/13 female) with plaque psoriasis and 15 control subjects (7 male/8 female)." (PMID 34272424, 2021). "Circulating CD4+ T lymphocytes from patients with psoriasis were also shown to have increased levels of GADD45b mRNA and protein." (PMID 34272424, 2021). "Our data demonstrate that GADD45a and GADD45b are upregulated in peripheral CD4+ T cells from psoriasis patients at basal conditions." (PMID 34272424, 2021). "In psoriasis, the function of GADD45b and other anti-inflammatory signals seems to be overcomed by pro-inflammatory triggers." (PMID 34272424, 2021). "Similar to the findings of RA patients, our data show that lesional skin from psoriasis patients express low levels of GADD45a and GADD45b." (PMID 34272424, 2021). "Although the expression of GADD45a and GADD45b molecules was diminished in non-stimulated moDCs from psoriasis patients compared to controls, after LPS stimulation both patients and controls were able to upregulate the expression of GADD45a and GADD45b at similar levels." (PMID 34272424, 2021).
renal carcinoma (2 papers, 2017). A carcinoma arising from the epithelium of the renal parenchyma or the renal pelvis. "In the present study, we showed that the treatment of human renal cancer cells with cordycepin inhibited TNF-α-mediated NF-κB/GADD45B signaling, which upregulated the MKK7-JNK signaling pathway activation through inhibition of c-FLIPL expression." (PMID 29045468, 2017). "We first examined whether the GADD45B mRNA was resistant to host shutoff upon lytic reactivation of a KSHV-positive B cell line (TREX-BCBL1) and a renal carcinoma cell line stably expressing the KSHV BAC16 (iSLK.219)." (PMID 28841715, 2017).